MANF (mesencephalic astrocyte derived neurotrophic factor)
Diseases named in the same sentence as MANF in open-access papers (continued):
Sharing a sentence is not in itself a finding about the gene and the disease.
Anxiety (4 papers, 2020 to 2025). Intense feelings of nervousness, tension, or panic often arise in response to interpersonal stresses. "We also performed elevated plus maze and open field tests and found significantly heightened anxiety in the MANF transgenic mice." (PMID 39425207, 2024). "MANF reduction also alleviated anxiety-related behaviors in 5xFAD mice as demonstrated by the elevated plus maze and open field tests." (PMID 39425207, 2024). "In the 9-month-old APP/PS1 mouse, VB reduced anxiety, improved memory and spatial cognition, suppressed the deposition of Aβ and tau protein phosphorylation, and decreased the overexpression of 4-HNE and MANF in the hippocampus." (PMID 33070776, 2020).
deafness (4 papers, 2018 to 2023). An inherited or acquired condition characterized by the complete loss of the ability to hear from one or both ears. "Similar symptoms of deafness, developmental delay, microcephaly, and short stature were found in two patients with childhood-onset diabetes lacking MANF because of mutation in the Manf gene." (PMID 35783104, 2022). "Absence of MANF relates to ER stress-triggered outer hair cell death and deafness." (PMID 37751132, 2023).
Hyperglycemia (4 papers, 2020 to 2023). An increased concentration of glucose in the blood. "Investigation of the role of MANF removal in the dopamine system was performed with Manffl/fl::NestinCre/+ mice, devoid of loss of pancreatic MANF and consequent hyperglycemia." (PMID 37555005, 2023).
myocarditis (4 papers, 2023 to 2026). Myocarditis is a condition that is characterized by inflammation of the heart muscle (myocardium). "demonstrate that, in checkpoint inhibitor induced myocarditis, induction of ERβ leads to downregulation of MANF and HSPA5 in female mice to increase ICI‐myocarditis in females." (PMID 41580387, 2026). "Estrogen receptor-β signaling was found to be necessary to maintain mesencephalic astrocyte–derived neurotrophic factor (MANF) transcription, whereas depletion of MANF worsened ICI myocarditis." (PMID 39023770, 2025).
retinal diseases (4 papers, 2017 to 2025). "However, further testing in retinal disease and traumatic injury is needed to understand the mechanisms of MANF’s action as well as its potential therapeutic effects." (PMID 31044581, 2019). "Unfortunately, we also had no data on whether MANF expression levels are associated with the progression of retinal diseases or the expression of other cytokines in the vitreous." (PMID 28367115, 2017). "Clearly MANF, as well as CDNF, have some anti-apoptotic and/or anti-inflammatory effects in models that utilize mechanical damage, and MANF is a potential target for retinal diseases." (PMID 31044581, 2019).
rheumatoid arthritis (4 papers, 2015 to 2024). A chronic, systemic autoimmune disorder characterized by inflammation in the synovial membranes and articular surfaces. "Several studies have demonstrated that MANF expression is increased in various pathological conditions associated with ER stress, including multiple myeloma, glomerular disease, rheumatoid arthritis, hepatic damage and systemic lupus erythematosus." (PMID 39242993, 2024). "In this study, we detected MANF expression in the peripheral white blood cells (PWBC) isolated from the patients with rheumatoid arthritis (RA) or systemic lupus erythematosus (SLE) and from rabbits with antigen-induced arthritis (AIA)." (PMID 25640174, 2015).
acute kidney injury (3 papers, 2022 to 2023). Sudden and sustained deterioration of the kidney function characterized by decreased glomerular filtration rate, increased serum creatinine or oliguria. "MANF has been proven to exert the anti-inflammatory effect in multiple inflammation-linked diseases, like acute kidney injury, bacterial myocarditis and antigen-induced arthritis." (PMID 35911675, 2022). "MANF not only participated in ER stress-related kidney disease, but also rescued acute kidney injury." (PMID 36639674, 2023). "Recent findings highlight its immune regulation during acute kidney injury through mono-macrophage-derived MANF." (PMID 37751132, 2023).
Autoimmunity (3 papers, 2016 to 2021). The occurrence of an immune reaction against the organism's own cells or tissues. "The colocalization of MANF with the mature oligodendrocyte cell body marker TPPP was not affected by treatment with dex indicating that dex only increased MANF-levels in myelinated axons, the primary targets of autoimmunity in EAE." (PMID 34305531, 2021). "This increased expression was highly co-localized with MBP-positive myelinated axons, the main targets of autoimmunity in EAE, while the colocalization of MANF with MBP was reduced along with MANF-levels during the peak of the disease." (PMID 34305531, 2021). "Furthermore, signs of autoimmunity against MANF were extremely rare in newly diagnosed patients, implying that MANF is not an important autoantigen in T1D." (PMID 27356471, 2016).
bacterial myocarditis (3 papers, 2022 to 2025). Myocarditis that is caused by an infection with a bacterial agent. "MANF also inhibits bacterial myocarditis and modulates M1 macrophage differentiation." (PMID 37751132, 2023).
brain injury (3 papers, 2018 to 2024). Acute and chronic (see also brain INJURIES, CHRONIC) injuries to the brain, including the cerebral hemispheres, CEREBELLUM, and brain STEM. "In a rat model of traumatic brain injury, MANF treatment decreased the levels of pro-inflammatory cytokines around the contusion." (PMID 35783104, 2022). "MANF, which also belongs to a novel evolutionarily conserved protein family, was reported to have the same neuroprotective effect after ischemic brain injury." (PMID 29966219, 2018). "Additionally, recombinant MANF has been shown to be neuroprotective in a rat model of traumatic brain injury, where the protective effect was attributed to increased BBB integrity and decreased activation of the NF-κβ signaling pathway." (PMID 35783104, 2022).
colitis (3 papers, 2023 to 2025). Inflammation of the colon. "To confirm the effect of MANF on macrophage infiltration, we evaluated the impact of myeloid cell-specific MANF deficiency on the subtypes of inflammatory cells in colitis environment." (PMID 36635421, 2023). "To address the mechanisms involved in the intestinal inflammation triggered by macrophage MANF deficiency, we sorted F4/80+ macrophages from colitis mouse colon tissues and performed RNA sequencing." (PMID 36635421, 2023). "We found that MANF deficiency in myeloid cells increased inflammation and disease severity in the colitis mouse model." (PMID 36635421, 2023). "Mechanistic studies revealed that the protective effect of MANF against colitis is associated with CHOP/BATF2-mediated regulation of inflammation in macrophages." (PMID 36635421, 2023). "Consistently, we found that in colitis, MANF deficiency in myeloid cells significantly upregulated CHOP expression." (PMID 36635421, 2023). "We further verified that MANF deficiency in myeloid cells exacerbated DSS-induced mice colitis." (PMID 36635421, 2023). "In summary, we have developed a new oral His-MANF colon-targeted delivery system to the inflammatory colon for the alleviation of colitis." (PMID 40115964, 2025). "This His-MANF oral formulation even enhanced colitis efficacy than His-MANF intravenous injection, suggesting a breakthrough from intravenous injection to oral administration, which would accelerate its translational medicine applications." (PMID 40115964, 2025). "We found that MANF expression was significantly increased in intestinal macrophages from both the mice with experimental colitis and patients with active IBD." (PMID 36635421, 2023). "MANF has been shown to improve colonic injury and negatively regulate macrophage polarization in colitis, indicating its potential as a therapeutic target for colonic inflammation." (PMID 37542061, 2023). "To confirm the effect of MANF on DSS-induced mice colitis, we treated MKO and WT mice with rhMANF by tail vein injection." (PMID 36635421, 2023). "This study uncovers the critical role of MANF in colonic macrophages which contributes to anti-inflammation and tissue repair in colitis." (PMID 36635421, 2023). "Both fluorescent imaging and immunohistochemistry staining results showed that His-MANF protein could accumulate in the colitis colon for a longer residence time after oral delivery." (PMID 40115964, 2025). "To further confirm the characteristic of MANF expression in inflammatory intestinal mucosa, we established DSS-induced colitis mouse model and found that MANF was significantly increased both in mRNA and protein levels in mice colon tissues after DSS treatment." (PMID 36635421, 2023). "Moreover, recombinant human MANF (rhMANF) protein administration alleviated the pathological damage of mice with colitis." (PMID 36635421, 2023). "Interestingly, we found that macrophage-derived MANF reduces the severity of colitis by inhibiting the recruitment of CX3CR1int proinflammatory macrophages and Th17 cells." (PMID 36635421, 2023). "We also established DSS-induced colitis in myeloid cell-specific MANF knockout (MKO) mice." (PMID 36635421, 2023). "In this study, we mainly focused on the impact of MANF on macrophages in colitis." (PMID 36635421, 2023). "In addition, we detected MANF expression in the peritoneal macrophages of mice with colitis." (PMID 36635421, 2023). "In another word, MANF functions as a negative regulator in macrophages to downregulate CHOP-BATF2 signaling pathway, thereby attenuated colitis." (PMID 36635421, 2023). "Our data indicate that MANF was significantly upregulated in the colonic mucosal tissues collected from IBD patients and experimental colitis mice, which was highly correlated with pathological colonic damage." (PMID 36635421, 2023).
colitis (continued). "To clarify the mechanisms of how MANF regulates macrophages, we analyzed the differential genes expressed in the colonic macrophages between WT and MKO colitis mice by RNA sequencing assay." (PMID 36635421, 2023). "To further confirm this result, we also double-labeled MANF and CD68 in colon tissues of mice with colitis." (PMID 36635421, 2023). "MANF proteins with His tags were found in the colon tissue of mice in both MSH@E and MS@E group, and MSH@E-treated colitis mice show greater accumulation than MS@E-treated colitis mice, which demonstrated that HA enhanced the localization within the inflamed colon." (PMID 40115964, 2025). "Therefore, MANF negatively regulates the expression of BATF2-mediated proinflammatory cytokines and chemokines in colonic macrophages, which may account for its role in controlling colitis." (PMID 36635421, 2023).
colon adenocarcinoma (3 papers, 2021 to 2024). "Here, we found that DLC1 was downregulated in CRC and overexpressed DLC1 promoted the secretion of MANF to inhibit colon adenocarcinoma cell migration." (PMID 36185184, 2022). "In summary, the present study showed that DLC1 interacted with GRP78 to increase the release of MANF, which inhibited the migration of wild-type colon adenocarcinoma cells." (PMID 36185184, 2022). "The results, which were in accordance with the ones treated with CM, indicated that MANF was the key factor for inhibition of colon adenocarcinoma cell migration." (PMID 36185184, 2022). "In comparison with the negative control (same concentration of BSA), the two colon adenocarcinoma cells treated with 200 ng/ml MANF decreased their ability to migrate, but there was no influence on proliferation." (PMID 36185184, 2022). "More importantly, exogenous MANF significantly inhibited the migration of colon adenocarcinoma cells HCT116 and SW1116, but did not affect proliferation." (PMID 36185184, 2022).
insulinoma (3 papers, 2018 to 2023). "In contrast, decreased MANF expression and increased MANF protein degradation was seen in rat insulinoma INS-1E cell line treated with cytokines or chemical ER stressors." (PMID 30386256, 2018). "To provide more insight into the MANF mechanism of action, we aimed to characterize its PPIs in human embryonic kidney HEK293 and rat insulinoma INS1 cell lines using AP-MS." (PMID 33460650, 2021). "MANF and CDNF protein–protein interactomes were characterized using affinity purification-mass spectrometry (AP-MS) in human embryonic kidney HEK293 and rat insulinoma INS1 cell lines induced to overexpress MANF or CDNF." (PMID 37555005, 2023).
Arthritis (2 papers, 2015 to 2021). Inflammation of a joint. "To further assess the expression characteristics of MANF in inflammatory tissue, we established rat and rabbit arthritis models and detected MANF in the two types of synoviocytes (MLS and FLS)." (PMID 25640174, 2015). "MANF mRNA is highly increased in peripheral white blood cells of RA patients as well as in the synovium of rabbit arthritis model, for which MANF was mainly localized in the cytoplasm of a-SMA-positive FLS and poorly in CD68-positive macrophage-like synoviocytes." (PMID 35008858, 2021).
brain infarction (2 papers, 2018 to 2019). Tissue necrosis in any area of the brain, including the cerebral hemispheres, the cerebellum, and the brain stem. "In addition, MANF-deficiency led to increased neuronal vulnerability to hypoxia/reperfusion as the brain infarction volume was significantly increased in experimentally induced focal cerebral ischemia in neuron-specific MANF-deficient mice." (PMID 30386256, 2018).
clear cell renal cell carcinoma (2 papers, 2025). "Our study delved into a novel mechanism through which ALKBH5 facilitated the transcription of MANF in clear cell renal cell carcinoma via a YTHDF2-dependent regulatory manner." (PMID 40603319, 2025). "Novel findings from RCC preclinical models reveal that MANF protein drives sunitinib resistance via IRE1α-XBP1 pathway inhibition, while NPTX2 aberrantly activates PI3K-Akt survival signaling in clear cell renal cell carcinoma (ccRCC)." (PMID 41142779, 2025).
Cognitive impairment (2 papers, 2024 to 2025). Abnormal cognition is characterized by deficits in thinking, reasoning, or remembering. "Similarly, mesencephalic astrocyte-derived neurotrophic factor (MANF) has been shown to attenuate sevoflurane-induced cognitive impairment." (PMID 40914484, 2025).
dementia (2 papers, 2021 to 2024). Loss of intellectual abilities interfering with an individual's social and occupational functions. "Our findings included well-known dementia-associated protein biomarkers, such as BMP4, CD200, MANF, PLXNB1, PLXNB3, and SMPD1 for AD and BCAN, NCAN, and THY1 for VD, as well as uncovering novel proteins associated with AD or VD." (PMID 39226887, 2024). "Additionally, the number of neurons in the ITGC with cytoplasmic MANF expression per unit area (1 mm2) was higher in pre-AD and AD patients than non-dementia control cases." (PMID 33994992, 2021). "In our study, we examined the expression of MANF in the ITGC of human brain specimens from pre-AD and AD patients and non-dementia control cases by immunohistochemistry." (PMID 33994992, 2021). "Mesencephalic astrocyte-derived neurotrophic factor expression in the ITGC of pre-AD, AD, and non-dementia control cases was evaluated by immunohistochemistry." (PMID 33994992, 2021).
glaucoma (2 papers, 2018 to 2022). Increased pressure in the eyeball due to obstruction of the outflow of aqueous humor. "Recent studies show that MANF protects CNS neurons and markedly improves RGC survival in a rat glaucoma model." (PMID 30245625, 2018). "In addition to p58IPK, recent studies identified mesencephalic astrocyte-derived neurotrophic factor (MANF) as an ER-localized neurotrophic factor, which inhibits ER stress-induced cell death of retinal neurons and improves RGC survival in a rat glaucoma model." (PMID 35346303, 2022).
inflammatory skin disease (2 papers, 2022). Inflammatory skin disorders covers a broad category that includes many conditions ranging in severity, from mild itching to grave medical health complications These disorders are common in people of all ages and races. "This study further expands MANF’s anti-inflammatory role in atopic dermatitis, possibly other skin inflammatory diseases." (PMID 35911675, 2022). "The relevance of ApoE, DKK1, IL12B, IL9, MANF, and VEGFC in specific inflammatory skin diseases was identified in several previous studies, as discussed further." (PMID 35393522, 2022).
liver cirrhosis (2 papers, 2022 to 2023). "MANF levels were associated with the status of liver cirrhosis, advanced tumour-node-metastasis (TNM) stage, and tumour size." (PMID 35057823, 2022).
liver disease (2 papers, 2023 to 2024). "MANF was originally identified as a member of a new NTFs family, its functions have been extensively studied, particularly in brain and liver disorders." (PMID 39289348, 2024). "These events indicated that MANF is highly expressed in liver and plays an important role in the regulation of liver disease." (PMID 37928262, 2023).
multiple epiphyseal dysplasia (2 papers, 2019 to 2021). Multiple epiphyseal dysplasias (MED/EDMs) are characterized by epiphyseal anomalies causing joint pain early in life, recurrent osteochondritis and early arthrosis. "In cellular models of multiple epiphyseal dysplasia MANF interacts with a V194D mutant of matrilin-3 that forms non-native disulfide bonds, suggesting that MANF functions as a part of ER stress response with other chaperones." (PMID 33460650, 2021). "MANF plays a cytoprotective role in several soft tissues and is upregulated in conditions resulting from intracellular retention of mutant protein, including two skeletal diseases, metaphyseal chondrodysplasia, Schmid type (MCDS) and multiple epiphyseal dysplasia (MED)." (PMID 30543055, 2019).
multiple sclerosis (2 papers, 2022 to 2025). A progressive autoimmune disorder affecting the central nervous system resulting in demyelination. "MANF has also shown protective effects on a mouse model of multiple sclerosis, where recombinant MANF-treated mice showed less motor deficits compared to vehicle-treated mice in an early time-point after experimental autoimmune encephalomyelitis induction." (PMID 35783104, 2022).
myocardial infarction (2 papers, 2024). Gross necrosis of the myocardium, as a result of interruption of the blood supply to the area, as in coronary thrombosis. "This study observed increased expression of MANF in both myocardial infarction patients and I/R mice." (PMID 39242993, 2024). "Elevated MANF levels have been observed in patients experiencing myocardial infarction and murine models of ischemia–reperfusion (I/R) injury, highlighting its importance in these conditions." (PMID 39462320, 2024). "Studies have shown that increased MANF levels during myocardial infarction act similarly to cardiomyokine in cardiomyocytes, potentially influencing cardiovascular function." (PMID 39242993, 2024). "In the current issue of Molecular Medicine, Dong, Jia and colleagues observed increased levels of MANF protein in both myocardial infarction (MI) patients and mice undergoing I/R injury, underscoring the crucial involvement of MANF in these pathological processes." (PMID 39462320, 2024).
renal cell carcinoma (2 papers, 2025). "This study was the first to show that MANF promoted tumor growth in renal cell carcinoma by reducing UPR through ALKBH5 epigenetic regulation." (PMID 40603319, 2025). "Taken together, our data indicated that elevated levels of the m6A demethylase ALKBH5 in renal cell carcinoma may lead to increased expression of downstream MANF, activating tumor cell UPR, and resulting in cells proliferation and invasion." (PMID 40603319, 2025). "The findings of this study indicated that the m6A eraser ALKBH5 upregulated MANF in a YTHDF2-dependent fashion, thereby conferring protection against ER stress-induced cell death in renal cell carcinoma." (PMID 40603319, 2025).